PLIN3 (perilipin 3)
Description:
Structural component of lipid droplets, which is required for the formation and maintenance of lipid storage droplets. Required for the transport of mannose 6-phosphate receptors (MPR) from endosomes to the trans-Golgi network.
Synonyms: PP17; M6PRBP1; TIP47
Tractability: Antibody: UniProt places it where antibodies can reach, with high confidence. PROTAC: UniProt records ubiquitination sites on it; ubiquitination databases record sites on it; its protein half-life has been measured.
Target class: Other cytosolic protein
Gene: Protein-coding gene on chromosome 19 (4,838,339 to 4,867,717, reverse strand). Ensembl gene ENSG00000105355.
Subcellular location: Lipid droplet; Endosome membrane; Cytoplasm
Subcellular location (Human Protein Atlas): Lipid droplets
Pathways (Reactome):
Autophagy: Chaperone Mediated Autophagy; Late endosomal microautophagy; Lipophagy
Metabolism: Triglyceride catabolism
Signal Transduction: RHOBTB3 ATPase cycle
Vesicle-mediated transport: Retrograde transport at the Trans-Golgi-Network
Gene Ontology:
Molecular function: cadherin binding; protein binding
Biological process: cellular response to glucose starvation; lipid droplet disassembly; lipid storage; positive regulation of triglyceride storage; vesicle-mediated transport
Cellular component: cytoplasm; endosome membrane; lipid droplet; membrane; cytosol; endosome; Golgi apparatus; transport vesicle
Genetic constraint (gnomAD): Loss-of-function variants: 32 observed, 35.43 expected, observed/expected ratio (o/e) 0.9, 90% interval 0.68 to 1.21. The upper end of that interval is the gene's LOEUF score, 1.21, which puts it in group 5 of 6, group 1 being the genes least tolerant of losing a copy. Missense variants: 599 observed, 603.01 expected, observed/expected ratio (o/e) 0.99, 90% interval 0.93 to 1.06. Synonymous variants: 258 observed, 264.65 expected, observed/expected ratio (o/e) 0.97, 90% interval 0.88 to 1.08.
Homologues: Orthologues: macaque PLIN3 (97% identical), chimpanzee PLIN3 (95% identical), dog PLIN3 (85% identical), mouse Plin3 (76% identical), guinea pig PLIN3 (75% identical), rat Ticam1 (72% identical), pig PLIN3 (68% identical), tropical clawed frog plin3 (51% identical), zebrafish plin3 (40% identical), Drosophila melanogaster Lsd-2 (17% identical). Paralogues in human: PLIN2 (41% identical), PLIN5 (38% identical), PLIN4 (31% identical), PLIN1 (24% identical).
Diseases named in the same sentence as PLIN3 in open-access papers:
PLIN3 is named in the same sentence as 65 diseases in open-access papers, as found by Europe PMC text mining. Sharing a sentence is not in itself a finding about the gene and the disease. The quoted sentences say what the papers report.
Hepatic steatosis (15 papers, 2014 to 2025). Steatosis is a term used to denote lipid accumulation within hepatocytes. "In our study, we confirmed that the protein levels of PLIN3 in HCC tissues is certainly associated with hepatic steatosis, and found that PLIN3 has the highest expression in HCC tissues accompanying with NAFLD." (PMID 37464334, 2023). "Our work is the first to show that inhibiting Plin3 in hepatocytes is sufficient to mitigate hepatocyte CGI-58 deficiency-induced hepatic steatosis and steatohepatitis in mice." (PMID 36107452, 2022). "Knockdown of hepatocyte Plin3 clearly alleviated hepatocyte CGI-58 deficiency-induced hepatic steatosis." (PMID 36107452, 2022). "We found that Plin3 knockdown in hepatocytes reduced hepatic steatosis, steatohepatitis, and necroptosis caused by hepatocyte CGI-58 deficiency in mice." (PMID 36107452, 2022). "Overall, the results demonstrate that Plin3 knockdown prevented hepatic steatosis in the HFD-fed hepatocyte CGI-58-deficient mice." (PMID 36107452, 2022). "In summary, the findings from this study identify hepatocyte PLIN3 as a protein essential for hepatic steatosis and NASH caused by hepatocyte CGI-58 deficiency in HFD-fed mice." (PMID 36107452, 2022). "In this study, we specifically tested whether silencing of hepatocyte Plin3 attenuates hepatic steatosis and steatohepatitis caused by hepatocyte-specific knockout of CGI-58 gene." (PMID 36107452, 2022). "Late-stage fatty liver down-regulates PLIN3 as an adaptive response; our data confirmed a concentration-dependent PLIN3 decrease." (PMID 41149615, 2025). "The majority of current researches focused PLIN3 on its role in liver steatosis, only a few studies paid attention to its function in cancers, and there has not a single study connecting PLIN3 with HCC so far." (PMID 37464334, 2023). "In our CDAA induced mouse NASH model, we found that the liver steatosis contributed to the expression changes of LDs localized proteins including PLIN3." (PMID 37464334, 2023). "Our study is the first to demonstrate that silencing a single lipid droplet coat protein PLIN3 can substantially attenuate hepatic steatosis and steatohepatitis in a murine model of advanced fatty liver disease." (PMID 36107452, 2022). "A recent paper discovered a new pathway linking PLIN3 and mTOR, in which PLIN3 was essential to activate lipophagy and protect against fatty liver worsening to steatohepatitis." (PMID 36364243, 2022). "The effect is associated with a downregulation of the expression of PPARγ, which is a marker of hepatic steatosis, and the upregulation of PLIN3, which is known to be involved in the activation of lipophagy." (PMID 36364243, 2022). "Depletion of hepatic Plin3 by antisense oligonucleotides reduces hepatic steatosis by 35%–52% in the mouse liver." (PMID 36107452, 2022). "Our result explained the mechanism behind this observation and indicated that perilipin-3 is a potential drug target to treat fatty liver disease." (PMID 30692541, 2019). "Virus-mediated knockdown of PLIN3 in the liver of high-fat diet fed mice improved hepatic steatosis along with glucose homeostasis." (PMID 27656402, 2016). "In transgenic mice fed either chow or a moderate-fat diet, PLIN3 knockdown reduced HCV core-induced steatosis, which showed that the cLD scaffold protein PLIN3 is required for HCV core-induced hepatic steatosis, which further shed light on the disease's pathophysiology." (PMID 37090186, 2023). "Similarly, PLIN3 has a significant role in promoting hepatic steatosis, as elevated levels of both PLIN2 and PLIN3 are reported in both human fatty liver biopsies and animal models of alcohol-related fatty liver disease." (PMID 32585865, 2020). "Additionally, expression levels of Plin2, a marker for hepatic steatosis, as well as Plin3 and Plin4, genes thought to mediate formation of nascent droplets, were also significantly elevated, suggesting increased synthesis and packaging of triglycerides." (PMID 27097220, 2016).
Hepatic steatosis (continued). "In hepatocytes, PLIN2 and PLIN3 are the major PAT protein family members that promote lipid storage, knockdown of each of which by antisense oligonucleotides can reduce diet-induced hepatic steatosis." (PMID 36107452, 2022). "In contrast to their wild-type littermates, Plin2KO mice fed alcohol do not develop hepatic steatosis despite the presence of Plin3 (a lipid droplet protein shown to compensate for Plin2)." (PMID 24831094, 2014). "Similarly, Tip47/Plin3-ASO affects liver LDs and improves liver steatosis." (PMID 36569303, 2022). "The lack of hepatic steatosis and reduced hepatic triglyceride levels in Plin2KO mice result from multifactorial effects on cellular lipid homeostasis, namely, a downregulation of de novo lipogenic and triglyceride synthetic pathways and a lack of compensation for Plin2 by Plin1 and Plin3." (PMID 24831094, 2014).
steatosis (9 papers, 2013 to 2026). Increased lipid within the cytoplasm of cells. "Plin3 knockdown in hepatocytes prevented steatosis, steatohepatitis, and necroptosis caused by hepatocyte CGI-58 deficiency." (PMID 36107452, 2022). "Plin3 knockdown likely hinders efficient formation and/or stability of intracellular lipid droplets, alleviating steatosis." (PMID 36107452, 2022). "Conversely, serum miRNAs associated with blunt steatosis specifically highlighted activity of FOXO1&HNF4α on CPT2, the lipid droplet and ER-lipid-raft associated PLIN3 and Erlin1." (PMID 27045805, 2016). "However, the reduction of PLIN3 has been shown to ameliorate steatosis and improve insulin sensitivity in models of MAFLD." (PMID 41559682, 2026). "Perilipin-2 and Perilipin-3 shield droplet cores from lipases; Perilipin-2 is abundant in non-adipose tissues and correlates with steatosis—PLIN2-null mice exhibit lower hepatic TG and resist diet-induced obesity." (PMID 41149615, 2025). "Therefore, the inhibition of lipophagy along with the continuous production of small LDs engulfed by PLIN2, PLIN3, and PLIN5 could be a proposed mechanism for NAFLD progression from simple steatosis to NASH." (PMID 37958873, 2023).
Insulin resistance (6 papers, 2013 to 2025). Increased resistance towards insulin, that is, diminished effectiveness of insulin in reducing blood glucose levels. "In humans, a study was performed to determine Plin3 levels among adults with varying degrees of obesity and insulin resistance, aiming to define the cardiometabolic associations of this protein." (PMID 39859272, 2025). "Overall, this study reports a significant inverse association between serum levels of PLIN3 and markers of insulin resistance among Saudi adults with T2DM." (PMID 34765049, 2021). "In this study, we aimed to compare for the first time PLIN3 levels among subjects with varying degrees of obesity and insulin resistance and to determine associations of PLIN3 with cardiometabolic indices." (PMID 34765049, 2021). "This study is aimed at determining levels of PLIN3 among adults with varying levels of obesity and insulin resistance to determine metabolic associations of PLIN3." (PMID 34765049, 2021). "It has been shown that the circulating PLIN3 is linked with insulin resistance in T2DM patients." (PMID 40572705, 2025). "Circulating PLIN3 is significantly associated with insulin resistance markers and maybe a promising candidate as a protective biomarker for T2DM." (PMID 34765049, 2021). "Therefore, circulating Plin3 could be a potential predictive biomarker for T2DM as it is significantly associated with insulin resistance indices." (PMID 39859272, 2025). "Our results showed significant reverse correlations between PLIN3 and insulin resistance indices (glucose, insulin, and HOMA-IR) in all groups." (PMID 34765049, 2021). "Despite these limitations, the study's findings have scientific merit as it sheds new light in the role of PLIN3 in the realm of human metabolism, insulin resistance in particular." (PMID 34765049, 2021). "BMI and WHR were inversely correlated with PLIN3 levels, as were the total cholesterol, triglycerides, and insulin resistance." (PMID 34765049, 2021). "Relatively lower expression of PLIN2 can promote the reduction of hepatic fibrosis and enhance insulin sensitivity, while simultaneously suppressing PLIN2 and PLIN3 can lead to insulin resistance." (PMID 29678171, 2018). "Hence, PLIN3 may be a promising marker for insulin resistance." (PMID 34765049, 2021). "But in each group, the reverse correlation between PLIN3 and insulin resistance indices was not significant, which may be due to the difference in the numbers of participants." (PMID 34765049, 2021).
Obesity (6 papers, 2014 to 2025). Accumulation of substantial excess body fat. "Circulating PLIN3 levels are influenced by obesity and T2DM status in Saudi adults, with the lowest levels observed in subjects having both conditions independent of sex." (PMID 34765049, 2021). "However, Plin3 seems to play an important function in obesity, promoting the transition from brown to white adipose tissue, and in cancer pathogenesis." (PMID 39859272, 2025). "Expression of PLIN4, which can prevent lysosomal degradation of cytosolic lipid droplets, was increased with age in WT mice and by both ethanol and obesity in 3xTg‐AD mice, whereas PLIN2 and PLIN3, which promote lysosomal degradation, were reduced." (PMID 40677154, 2025). "In lean MASLD, metabolic stress in the absence of overt obesity may promote lipid droplet remodeling or impair vesicular trafficking, leading to reduced PLIN3 incorporation into EVs relative to CD63." (PMID 41295331, 2025). "The alteration in the PLIN3/CD63 ratio may thus occur during an early or metabolically dysregulated stage of MASLD independent of obesity." (PMID 41295331, 2025).
prostate carcinoma (5 papers, 2021 to 2025). A carcinoma that arises from epithelial cells of the prostate gland. "upregulation of ACSS3 in prostate cancer cells regulates PLIN3 stability, reduces lipid droplet deposition, and induces ER stress-mediated apoptosis, reversing enzalutamide resistance and hindering castration-resistant prostate cancer progression." (PMID 41145471, 2025). "High PLIN3 expression in prostate cancer was positively correlated with tumor stage and Gleason score." (PMID 35053570, 2022). "In prostate cancer, PLIN3 overexpression promotes tumor progression." (PMID 38554152, 2024).
breast carcinoma (3 papers, 2022 to 2025). "Elevated PLIN3 levels have been observed in multiple malignancies, including HCC, breast cancer, colon cancer, and lung cancer." (PMID 41041279, 2025).
cervical carcinoma (3 papers, 2020 to 2023). A carcinoma arising from either the exocervical squamous epithelium or the endocervical glandular epithelium. "Elevated levels of PLIN3 expression were observed in patients with cervical cancer, decreased after treatment, and elevated PLIN3 was found again at recurrence." (PMID 37189627, 2023). "PLIN3 is a blood marker of cervical cancer and biomarker of cervical developmental disorders and invasive cancers." (PMID 32368290, 2020). "Studies have shown that the growth of cervical cancer cells with knocked-out PLIN3 was inhibited." (PMID 32368290, 2020).
hepatoma (3 papers, 2013 to 2023). "To further validate the function of PLIN3 in hepatoma cells, we first constructed PLIN3 knockdown cell lines, including HepG2 and LM3, by shRNA lentivirus, and the knockdown efficiency was confirmed by qRT-PCR." (PMID 37464334, 2023). "Thus, we took PLIN3 as a targeting protein to reveal the function of LDs localized proteins in the malignant progression of hepatoma cells." (PMID 37464334, 2023). "Combine with the function of PLIN3 identified in hepatoma cells, we speculated that PLIN3 might be an important factor in the progression of NAFLD to HCC." (PMID 37464334, 2023). "Besides, transwell assay revealed that the knockdown of PLIN3 remarkably impeded the migration and invasion of Hepatoma cells." (PMID 37464334, 2023). "It has been found that PLIN3 could affect the invasion and chemosensitivity of hepatoma cells, indicating the participation of PLIN3 and other LDs localized proteins in HCC progression." (PMID 37464334, 2023). "The mechanism of PLIN3 in sorafenib and doxorubicin induced the apoptosis of hepatoma cells may be attributed to autophagy." (PMID 37464334, 2023). "The results showed that the knockdown of PLIN3 could enhance the cytotoxicity of sorafenib, doxorubicin and cisplatin in Hepatoma cells." (PMID 37464334, 2023). "Finally, we performed western blot to detect the apoptosis induced by these chemotherapeutic agents, and found that the cytotoxicity enhancement of PLIN3 knockdown in hepatoma cells may attributed to the increased apoptosis levels." (PMID 37464334, 2023). "Moreover, we explored if PLIN3 participated in the chemosensitivity of Hepatoma cells." (PMID 37464334, 2023). "Functional studies revealed that PLIN3 knockdown significantly limited the migration and chemosensitivity of hepatoma cells, suggesting the positive role of PLIN3 in HCC progression." (PMID 37464334, 2023). "Furthermore, we took PLIN3 as the object to explore its function in the behavior of hepatoma cells." (PMID 37464334, 2023). "Knockdown of PLIN3 in hepatoma cells affected their migration and invasion, and it further had an influence on the cytotoxicity and apoptosis of sorafenib and doxorubicin on hepatoma cells, indicating that PLIN3 could affect the chemosensitivity of hepatoma cells." (PMID 37464334, 2023).
atherosclerosis (2 papers, 2025). A disease characterized by the build-up of fatty material and calcium deposition in the arterial wall resulting in partial or complete occlusion of the arterial lumen. "Moreover, Plin3 expression is directly enhanced by the combination of elevated serum levels of glucose, insulin, and free FAs, which are major risk factors promoting atherosclerosis or CVDs." (PMID 39859272, 2025). "Therefore, Plin3 could be another potential molecular target for the prevention or therapy of atherosclerosis." (PMID 39859272, 2025).
clear cell renal cell carcinoma (2 papers, 2020 to 2024). "Kaplan–Meier curves revealed that elevated PLIN3 predicted poor DFS and OS in clear cell renal cell carcinoma." (PMID 38554152, 2024).
glioma (2 papers, 2021 to 2023). A benign or malignant brain and spinal cord tumor that arises from glial cells (astrocytes, oligodendrocytes, ependymal cells). "Survival analysis showed that PLIN2 and PLIN3 expression did not correlate significantly with the survival prognosis of GBM patients, but was associated with shorter survival in LGG patients, and that PLIN2/PLIN3 overexpression was correlated with the malignant phenotype of gliomas." (PMID 37189627, 2023). "Our findings suggested that PLIN2 and PLIN3 expression levels were elevated in glioma." (PMID 37189627, 2023). "Similar trend was observed for PLIN3 in low-grade glioma patients." (PMID 34499029, 2021). "Therefore, the high expression of PLIN2 and PLIN3 in glioma might be related to the malignant progression of glioma and this needs further exploration." (PMID 37189627, 2023). "Furthermore, we observed that the expression levels of PLIN2 and PLIN3 were higher in the recurrent tissues than in the primary tumors, indicating that they may play essential roles in the development and recurrence of gliomas." (PMID 37189627, 2023). "mRNA levels of PLIN2 and PLIN3 were not statistically different between grade II and grade III, and the highest mRNA levels of both were expressed in grade IV glioma tissues." (PMID 37189627, 2023).
Hepatic fibrosis (2 papers, 2014 to 2018). The presence of excessive fibrous connective tissue in the liver. "We also identified several new genes, such as perilipin-3, legumain, and myocilin, which were associated with liver fibrosis." (PMID 25380136, 2014).
lung adenocarcinoma (2 papers, 2021 to 2024). A carcinoma that arises from the lung and is characterized by the presence of malignant glandular epithelial cells. "Previous studies linked high PLIN3 expression with shorter survival time in other tumor types, such as lung adenocarcinoma." (PMID 39201394, 2024). "Moreover, elevated PLIN3 expression has recently been related to poor prognosis of lung adenocarcinoma, whereas ablation of PLIN3 inhibited the invasion ability of lung adenocarcinoma cells." (PMID 34067931, 2021).
lung carcinoma (2 papers, 2022 to 2025). "Lipid droplet surface protein, PLIN3, was found frequently overexpressed since the early stage in lung cancer tissues." (PMID 36293388, 2022). "The expression levels of PLIN2 and PLIN3 tend to be higher in lung cancer cell lines than normal ones, and the levels of PLIN3 better recapitulate the amount of LD than the levels of PLIN2, except for the high PLIN3 expression in a low LD cell line, WI-38 cells." (PMID 36293388, 2022).
renal cell carcinoma (2 papers, 2021 to 2023). "PLIN3 serves as a potential diagnostic and prognostic biomarker in renal cell carcinoma, and its expression is upregulated in renal cell carcinoma cells and tissues." (PMID 34925365, 2021). "In renal cell carcinoma, PLIN2 expression was correlated with a favorable prognosis, but the high expression of PLIN3 is correlated with a poor prognosis." (PMID 37998612, 2023).